APP (amyloid beta precursor protein)
Diseases named in the same sentence as APP in open-access papers (continued):
Sharing a sentence is not in itself a finding about the gene and the disease.
Cognitive impairment (continued). "In the MWM test, AD mice exhibited a longer time to find the target quadrant and a lower frequency of platform crossings than WT mice (both p < 0.001); however, AET treatment significantly improved cognitive deficits in APP/PS1 mice (all p < 0.01)." (PMID 41249871, 2025). "It has previously been shown that Akkermansia administration to APP/PS1 mice is associated with significant reduction of Aβ load in the cortex and amelioration of cognitive deficits." (PMID 40444050, 2025). "Knockout of Galectin‐9 substantially attenuates Aβ pathology and cognitive impairment in APP/PS1 mice." (PMID 39485716, 2025). "The Morris water maze test and nest test showed that DNLA administration significantly delayed the appearance of cognitive deficits in APP/PS1 mice." (PMID 40047153, 2025). "Quercetin can treat the cognitive impairment behaviors and AD pathological manifestations in APP/PS1 double transgenic mice." (PMID 41048351, 2025). "To explore this, we applied dfPPI to female APP NL-F mice at 7 months of age—when cognitive deficits begin to appear—and 15 months of age—when cognitive deficits become more severe—along with age-matched wild-type (WT) controls." (PMID 39989971, 2025). "Nevertheless, considering the enhancing effect of L-lactate on APP lactylation, a major contributor to Aβ production, we believe that L-lactate treatment has a positive impact on alleviating AD pathology and cognitive deficits." (PMID 39744941, 2025). "In this study, we demonstrated that EA at ST36 and ST37 alleviates neuroinflammation and cognitive deficits in APP/PS1 double transgenic mice via gastric vagal afferent-mediated activation of the NTS ‒ LC noradrenergic circuit." (PMID 41233833, 2025). "Given that TAU and APP aggregation correlate with the severity of cognitive impairment in AD patients, we assessed memory in mice." (PMID 41164084, 2025). "Taken together, these results demonstrate that APP-K612la significantly reduces Aβ generation and ameliorates synaptic and cognitive impairments in vivo." (PMID 39744941, 2025). "Endothelial cell-specific knockdown or treatment with a monoclonal antibody was used to assess the functional consequences on cognitive impairment and AD pathology via two-photon imaging and behavioral experiments on APP/PS1 mice." (PMID 40702549, 2025). "Our findings demonstrate elevated levels of APP and phosphorylated tau in the hippocampi of mice chronically exposed to METH, indicating neuronal damage associated with cognitive impairment." (PMID 40003980, 2025). "The effect of Ginsenoside Ro on memory and cognitive impairment in APP/PS1 mice was assessed using the MWM test." (PMID 40066331, 2025). "The administration of Agathobaculum butyriciproducens (SR79), a butyric acid‐producing bacterium, has been found to ameliorate microglial activation and cognitive impairments in APP/PS1 transgenic and LPS‐induced cognitive impairment mouse models." (PMID 39957504, 2025). "While certain murine models of AD suggest a worsening of pathology in females, we did not observe any profound differences in the progression of pathological markers or cognitive impairments between males and females in APP/PS1 mice." (PMID 40004200, 2025). "Several associations between CNV mutations in genes (APP, GRN, MAPT, PSEN1, PSEN2) and various domains of cognitive impairment were identified." (PMID 40725212, 2025). "Genetic deletion of AEP in APP/PS1 and 5XFAD transgenic mice attenuates AD-associated pathologies, including synaptic loss, Aβ deposition, amyloid plaque burden, and cognitive impairment." (PMID 40816999, 2025). "This study explored TMF’s pharmacological effects in AD models, highlighting its ability to improve memory and cognitive deficits in APP/PS1 mice." (PMID 39997198, 2025). "Despite APP/PS1 transgenic models linking amyloid pathology to cognitive deficits, clinical translation faced challenges due to CSF invasiveness and poor early-stage correlation." (PMID 40606501, 2025).
Cognitive impairment (continued). "As a flavonoid-rich vegetable, we previously demonstrated that safflower leaves can ameliorate cognitive impairment, reduce oxidative damage, and inhibit neuroinflammation in APP/PS1 mice." (PMID 41462694, 2025). "The PDAPP mouse model expresses three isoforms of APP, leading to excess Aβ and early formation of amyloid plaques, with spatial memory impairments at 6 months of age, mimicking early cognitive impairments of AD patients." (PMID 40420360, 2025). "For instance, walnut-derived peptide ameliorated cognitive impairments while increasing the relative abundance of Bacillota in the feces of APP/PS1 mice." (PMID 40509464, 2025). "Muribaculum has been described to play a protective role in the development of cognitive impairment in APP/PS1 transgenic mice, a murine model of AD." (PMID 38919500, 2024). "They effectively enhance beneficial bacteria such as Bifidobacteria and Lactobacilli, improving cognitive impairment in APP/PS1 mice through the gut-brain axis." (PMID 38627829, 2024). "Research has found that probiotic SB treatment significantly alleviates cognitive deficits, Aβ aggregation, synaptic dysfunction, neuroinflammation, intestinal barrier impairment, and fungal microbiome abnormalities in APP/PS1 mice." (PMID 39416793, 2024). "Amyloid accumulation and subtle cognitive impairments are observed at 6 months of age and rapidly progress to 12 months in APP/PS1 mice." (PMID 39614130, 2024). "Activated AEP then cleaved APP and tau, resulting in tau1–368 formations, and consequentially accelerated Aβ deposit and Tau hyperphosphorylation, resulting in cognitive impairment." (PMID 38114762, 2024). "Orally administered taurine with drinking water can ameliorate cognitive impairment by directly binding to oligomeric Aβ in APP/PS1 transgenic mice." (PMID 38548872, 2024). "Taken together, administration of 5a effectively restores learning and memory impairment in mice with scopolamine-induced cognitive impairment and APP/PS1 mice." (PMID 39431021, 2024). "The 5xFAD mouse model, generated by combining three human APP mutants with two PS1 mutations, exhibited early-onset amyloidosis, cognitive impairment, and neuronal loss." (PMID 38419106, 2024). "Subsequently, we performed Western blots to assess the protein level of amyloid precursor protein (APP) and β-site APP cleaving enzyme-1 (BACE1) in the hippocampus, a phenomenon associated with cognitive impairment." (PMID 39200168, 2024). "The pharmacological activation of PPAR-α receptors stimulated autophagy in the microglia as well as in the cells expressing human APP, also decreasing Aβ accumulation and attenuating cognitive impairment in AD-like mice." (PMID 39596118, 2024). "Improved cognitive impairment; reduced Aβ and APP expression and inhibited neuronal apoptosis; activation of TrkA signaling and inhibition of p75NTR signaling." (PMID 39149548, 2024). "This study clearly showed that FMN was effective in preserving the learning and memory abilities and ameliorating anxiety and depression in SAMP8 mice, which is consistent with the role of FMN in improving cognitive deficits in APP/PS1 mice." (PMID 39234102, 2024). "When Poria cocos extract was administered by gavage at 1.2 g/kg/day for 3 months, the abundances of Deferribacteraceae, Lachnospiraceae, and Enterobacteriales were decreased and cognitive impairment was alleviated in APP/PS1 mice." (PMID 39508315, 2024). "Widely used to induce memory or cognitive deficits in rodent models for dementia-related studies, scopolamine-driven neurodegeneration in rats is reported, including increased Aβ protein, APP mRNA levels, phosphorylated tau, and GSK-3β levels." (PMID 38397402, 2024). "Even at pre-plaque stages, the intraneuronal accumulation of Aβ peptides provokes cognitive deficits in APP transgenic rats." (PMID 39707506, 2024).
Cognitive impairment (continued). "Overexpression of miR-140 and miR-122 in CNS induced cognitive impairment in wild-type mice and exacerbated cognitive dysfunction in APP/PS1 mice." (PMID 38956605, 2024). "TMAO supplementation has been shown to induce cognitive impairment in APP/PS1 mice by promoting neuroinflammation, Aβ and tau pathology." (PMID 38360862, 2024). "Impaired GABAergic transmission mediates upregulated epilepsy susceptibility, triggers hippocampal circuit cascade damage, and exacerbates cognitive impairment in APP/PS1 mice." (PMID 38388921, 2024). "Other mouse models (Tg2576 APP transgenic mice and APP/PS1) performed damaged, round, and swollen mitochondria coinciding with loss of oxidative activity and preceding the beginning of cognitive impairment and β-amyloid plaque creation." (PMID 38457008, 2024). "We demonstrated that cystatin F expression was specifically elevated in the monocytes of sporadic AD patients and that in vivo, human cystatin F aggravated Aβ deposition in the brain and cognitive impairment in APP/PS1 mice." (PMID 38730470, 2024). "As previous studies reported, APP/PS1 mice exhibit cognitive deficits from 6 to 8 months of age and present decreased synaptophysin levels at 7–8 months." (PMID 39696695, 2024). "Monocyte-derived cystatin F increased Aβ deposition and exacerbated cognitive deficits in APP/PS1 mice." (PMID 38730470, 2024). "An animal study showed that a 4-week treatment with Clostridium butyricum (5 × 108 CFU/day) effectively protected against cognitive impairment and amyloid pathology by reducing microglia-mediated neuroinflammation in an AD (APP/PS1) mouse model." (PMID 38414054, 2024). "We observed that LIG‐loaded liposome (LIG‐LPs) treatment reduced oxidative stress and β‐amyloid (Aβ) deposition and mitigated cognitive impairment in APP/PS1 mice." (PMID 37718506, 2024). "Bifdobacterium Lactis Probio-M8 can reduce the deposition of Aβ plaque in the whole brain, prevent the imbalance of intestinal flora, and alleviate the cognitive impairment of APP/PS1 mice." (PMID 37728579, 2024). "Our results indicate that TBN significantly alleviated cognitive impairment and reduced Aβ deposition in APP/PS1 mice." (PMID 39204110, 2024). "The δ‐secretase, activated in the aging brain, is the key enzyme in the cleavage of APP and Tau, ultimately leading to cognitive impairment." (PMID 38644578, 2024). "APP/PS1 strain shows cognitive impairment relatively later (at 10‐12 months), and the 3xTg is the only one with tau‐related mutations, with cognitive impairment appearing around 3−6 months, and Aβ deposition occurring after 9 months of age." (PMID 39415847, 2024). "Monocyte-derived cystatin F exacerbate Aβ deposition in the brain and cognitive impairment in APP/PS1 mice." (PMID 38730470, 2024). "The BACE1 causes the accumulation of β-cleaved C-terminal fragment C99 and full-length amyloid precursor protein (fl-APP) in the mitochondria, leading to mitochondrial dysfunction and cognitive impairment." (PMID 39796097, 2024). "In this study, 9‐MF at low concentrations significantly prevented cognitive impairments with similar efficacy as donepezil in APP/PS1 transgenic mice." (PMID 39563011, 2024). "Overexpression of miR-140 and miR-122 in the hippocampus induced cognitive impairment in wild type C57 mice and exacerbated cognitive deterioration in APP/PS1 mice." (PMID 38956605, 2024). "APP and PSEN1 mutations in mouse neurons have been shown to induce behavioral and cognitive deficits in different mouse models." (PMID 38473822, 2024). "In an APP-transgenic mouse model with genetic inactivation of PSEN1, synaptic and cognitive deficits correlated with presynaptic APP-CTF accumulation." (PMID 38951839, 2024). "Our work suggests that RHBDL4’s increased expression in AD, in addition to regulating APP levels, leads to aberrant degradation of β-catenin, contributing to cognitive impairment." (PMID 38464180, 2024).
Cognitive impairment (continued). "Sulforaphane administration ameliorates cognitive impairment and reduces Aβ accumulation in the brains of 5xFAD mice with five human mutations in APP and PS1 and 3xTg-AD lines with three human mutations in APP, PS1, and TAU." (PMID 39765857, 2024). "In particular, 5-HT2A receptors have been reported to regulate the proteolytic cleavage of APP, neuroinflammation and cognitive deficits." (PMID 38992700, 2024). "Chronic metformin administration was found to ameliorate synaptic malfunctions and cognitive impairment in the amyloid precursor protein (APP)swe/presenilin-1(PS1)DE9 (APP/PS1) mouse model of AD via the inhibition of cyclin-dependent kinase 5 (Cdk5) activity." (PMID 38132442, 2023). "In this study, we present evidence that sleep disturbances, especially reduced slow-wave activity during sleep, precedes the development of cognitive impairments in APP/PS1 mice." (PMID 37433857, 2023). "In another study, LV-based expression of the anti-aging gene Klotho efficiently ameliorated cognitive deficits and Alzheimer’s disease-like pathologies in the brains of APP/presenilin-1 transgenic mice." (PMID 36992407, 2023). "A recent study has proposed that Eggerthellaceae, Rodentibacter, Bacteroides, Ruminococcaceae_UCG_014, Faecalibaculum, and Muribaculaceae were increased after surgery in APP/PS1 mice with cognitive impairment." (PMID 37113132, 2023). "27-hydroxycholesterol promotes Aβ accumulation in mild cognitive impairment patients and in the APP/PS1 mouse AD model." (PMID 36845656, 2023). "Studies have shown that early transient depletion of Tregs accelerate cognitive impairment and amplification of Tregs through peripheral IL-2 treatment restored cognitive function in APP/PS1 mice." (PMID 38023614, 2023). "Necroptosis is activated in brains of AD human and AD mice, and suppression of necroptosis exerts a neuroprotective effect on cognitive impairment in AD mouse model: 5xFAD and APP/PS1 mice." (PMID 37740205, 2023). "The normalization of perivascular Aqp4 mislocalization, with the addition of 5-caffeoylquinic acid, led to increased Aβ clearance and improved cognitive impairment in an APP/PS2 AD mouse model." (PMID 37762391, 2023). "Similar to the effect of IL-33 injection that reversed cognitive deficits in APP/PS1 mice, MS1262 inhibition of G9a upregulated IL-33 expression." (PMID 38045363, 2023). "The potential therapeutic effect of M30 on AD-related neuropathology and cognitive deficits was investigated in APP/PS1 double Tg mice, a well-established AD mouse model." (PMID 36899898, 2023). "It has been shown that APP/PS1 mice have reduced spine density in CA1 pyramidal neurons which leads to impairment of synaptic connectivity and is associated with cognitive impairment." (PMID 36743440, 2023). "During the process of microglial synapse phagocytosis, Aβ was also engulfed and degraded, such Aβ clearance improved CNS microenvironment, gradually promoted synapse regeneration and recovery, and reversed cognitive deficits in antibody-treated APP/PS1 mice." (PMID 36693826, 2023). "The production and accumulation of large amounts of Aβ peptides can promote the formation of SPs and lead to cognitive impairment in APP/PS1 mice." (PMID 36681681, 2023). "The current study demonstrates that chronic M30 treatment improved cognitive impairment and attenuated Aβ accumulation and tau phosphorylation in various brain regions of APP/PS1 Tg mice, compared with vehicle treated Tg mice." (PMID 36899898, 2023). "Injection of honokiol seem to relieve cognitive impairment in APP/PS2 mice by eliciting the UPRmt65." (PMID 37705748, 2023). "Depletion of Treg cells in the APP/PS1 mouse model reduced recruitment of β-amyloid plaque-associated microglial cells and accelerated cognitive impairment." (PMID 36703235, 2023).
Cognitive impairment (continued). "Long term effects of TBI in humans and mouse models include cognitive deficit, deposition of amyloid precursor protein (APP), amyloid-beta peptide and tau protein intracellular neurofibrillary tangles." (PMID 37663654, 2023). "The same phenomenon was observed in advanced-stage APP/PS1 mice with significant cognitive deficits." (PMID 37433857, 2023). "As expected, aged APP/PS1 mice exhibited severe deficits in spatial memory whereas APP/PS1/NLRP3-/- mice were protected from this cognitive impairment." (PMID 37509487, 2023). "In the present study, chronic Baicalein treatment for 14 days significantly reversed cognitive deficits in 8-month-old APP/PS1 mice." (PMID 37063260, 2023). "We demonstrated APP/PS1 mice displayed cognitive impairment and hippocampal neuronal damage, accompanied by autophagy dysfunction." (PMID 36681681, 2023). "Age and sex are important variables to consider in evaluating periodontal bone tissue, and the cognitive impairment of APP/PS1 mice is more related to age." (PMID 37370108, 2023). "BBR ameliorates Alzheimer’s pathology and cognitive impairment of APP/PS1 mice induced by D-ribose through inhibiting PINK1 promoter methylation." (PMID 36982968, 2023). "Since the p35-GluR1-CaMKII complex is important for synaptic plasticity, learning, and memory, this decrease in the formation of the complex resulting from SIS leads to memory and cognitive impairment in APP/PS1 mice." (PMID 37163426, 2023). "In APP/PS1 transgenic mice and 3xTG-AD mice, several months of MN-08 daily treatments attenuated Aβ accumulation, neuronal and dendritic spine loss, and cognitive deficits." (PMID 37400870, 2023). "EXs derived from hypoxia-preconditioned mesenchymal stromal cells were shown to rescue cognitive impairment in the Alzheimer APP/PS1 mouse model, while ischemic preconditioned astrocyte-derived EXs can protect neurons from apoptosis." (PMID 37685965, 2023). "Exposure to menthol for 6 months (1 week per month) prevented the cognitive impairment observed in the APP/PS1 mouse model of Alzheimer." (PMID 37187754, 2023). "CQA treatment ameliorated cognitive impairments in APP/PS1 mice by increasing the activation of certain signalling pathways." (PMID 36982837, 2023). "The MWM test was used to detect and evaluate the spatial learning and memory capacities of APP/PS1 mice to examine the effects of ICA on their cognitive deficits." (PMID 37095548, 2023). "In conclusion, we found that KXS had neuroprotective characteristics, as it prevented cognitive deficits in APP/PS1 mice." (PMID 36918872, 2023). "A16 induced cognitive deficits in APP/PS1 mice, with reduced residence time in the novel arm of Y-maze and decreased discrimination index in the NOR test." (PMID 36693826, 2023). "The anti-AD effects of OST/BO thus exhibited much better efficiency in improving cognitive impairment in APP/PS1 mice than OST alone." (PMID 37521471, 2023). "Consistent with the previous studies, our study revealed that ICA reversed the cognitive impairment and histopathological alterations in the APP/PS1 mice." (PMID 37095548, 2023). "Cui and colleagues revealed that EXs derived from hypoxia-preconditioned mesenchymal stromal cells can rescue cognitive impairment in the Alzheimer APP/PS1 mouse model." (PMID 37685965, 2023). "EVs secreted from adipose-derived MSC effectively ameliorated neurodegeneration and rescued cognitive impairment in APP/PS1 transgenic mice, a classic AD mice model." (PMID 36559145, 2022). "Intravenous administration of HA-MMSN-1F12 for three weeks significantly reduced brain Aβ burden, neuroinflammation, and cognitive deficits in APP/PS1 mice." (PMID 36185606, 2022). "Here, we investigate the potentially protective effects of Xn on cognitive impairment in APP and presenilin 1 (PS1) double-transgenic mice, while screening key components of the gut microbiome via 16S rDNA sequencing." (PMID 35209070, 2022).